RAB18 (RAB18, member RAS oncogene family)
Diseases named in the same sentence as RAB18 in open-access papers (continued):
Sharing a sentence is not in itself a finding about the gene and the disease.
glioma (2 papers, 2021 to 2022). A benign or malignant brain and spinal cord tumor that arises from glial cells (astrocytes, oligodendrocytes, ependymal cells). "We provide evidence that Rab18 plays a role in proliferation and apoptosis of glioma cells, as well as the sensitivity for TMZ through interacting with VSIG4." (PMID 33904378, 2021). "Rab18 and V-set and immunoglobulin domain-containing 4 (VSIG4) were reportedly implicated in the malignant progression of glioma." (PMID 33904378, 2021). "Clear evidence has pointed out the close relationship between Rab18 expression and prognosis and histopathology of glioma, as upregulation of Rab18 was involved in the worst outcome of glioma patients." (PMID 33904378, 2021). "To identify the role of membrane trafficking protein RAB18 in glioma, we first analyzed its expression through searching for BioGRID4.2 database, and found notable increased RAB18 expression." (PMID 33904378, 2021). "To further investigate the role of RAB18 in glioma, we used siRNA to interfere with RAB18 expression in U251-MG and U87-MG cells." (PMID 33904378, 2021). "To explore the roles of Rab18 and VSIG4 in glioma, we silenced Rab18 or overexpressed VSIG4 to detect the proliferation and apoptosis of cells, as well as the relationship between Rab18 and VSIG." (PMID 33904378, 2021). "However, it remains elusive regarding the molecular mechanism by which Rab18 exerted effects on the pathophysiology of glioma." (PMID 33904378, 2021). "The study lay a crucial foundation for the development of drugs targeting Rab18 or VSIG4, and provide a novel sight for understanding of the pathophysiology of glioma." (PMID 33904378, 2021). "Our study first confirmed that there existed an interaction between Rab18 and VSIG4 in glioma cells." (PMID 33904378, 2021). "All in all, these findings suggest that targeting the interaction of Rab18 and VSIG4 could contribute to marked efficacy in glioma while provides novel sights for understanding the pathogenesis of glioma and developing new therapeutical methods." (PMID 33904378, 2021). "Targeting the interaction between Rab18 and VSIG4 may help exploit new therapies to enhance TMZ sensitivity for treating patients with glioma." (PMID 33904378, 2021). "Based on these, we proposed that a possible interaction of Rab18 and VSIG4 could be involved in the progression of glioma." (PMID 33904378, 2021).
non-small cell lung carcinoma (2 papers, 2014 to 2021). A group of at least three distinct histological types of lung cancer, including non-small cell squamous cell carcinoma, adenocarcinoma, and large cell carcinoma. "In addition, interference of RAB18 suppressed cell viability of non-small-cell lung cancer." (PMID 34135963, 2021).
colorectal cancer (1 paper, 2020). A primary or metastatic malignant neoplasm that affects the colon or rectum. "In addition, RAB18 is reported to be highly expressed in colorectal cancer and closely related to poor survival in patients." (PMID 32432324, 2020).
diabetic nephropathy (1 paper, 2022). "It was also observed that hispidulin modulated multiple Pim1-interacted proteins such as NRAS and RAB18 to regulate the development of diabetic nephropathy." (PMID 34028657, 2022).
fibrosis (1 paper, 2023). the formation of excess fibrous connective tissue in an organ or tissue in a reparative or reactive process. "Taken together, our results from the fibrosis model are compatible with the reported role of Rab18 in LD growth." (PMID 38139006, 2023).
Insulin resistance (1 paper, 2024). Increased resistance towards insulin, that is, diminished effectiveness of insulin in reducing blood glucose levels. "Moreover, a recent study highlighted the involvement of Rab18 in lipid metabolism in human diabetic adipose tissue and demonstrated that Rab-18 contributes to insulin resistance in obese individuals." (PMID 37873477, 2024).
liver fibrosis (1 paper, 2025). "Targeting RAB18 and inhibiting lipophagy to induce cuproptosis can effectively slow down the pathological progression of liver fibrosis." (PMID 40213908, 2025). "This process not only deepens our understanding of the regulatory mechanisms of lipophagy and copper death in liver fibrosis but also highlights RAB18 as a key bridge between lipophagy and copper death, playing a crucial role in HSCs." (PMID 40213908, 2025). "In both liver fibrosis models, the progression of fibrosis was significantly aggravated after knocking down RAB18 expression in the liver using AAV8‐RAB18KD." (PMID 40213908, 2025). "The detection of liver injury‐related enzymes (ALT, AST, and ALP) and liver fibrosis markers (IV‐C, PC‐III, HA, SMA, Hyp, and LN) also showed that RAB18 knockdown significantly promoted the progression of liver fibrosis." (PMID 40213908, 2025). "In summary, these results suggest that RAB18 plays a critical role in the progression of liver fibrosis by regulating lipophagy and cuproptosis." (PMID 40213908, 2025). "First, we assessed the correlation between RAB18 expression and the progression of liver fibrosis by analyzing clinical liver pathology samples." (PMID 40213908, 2025). "The results showed that in both liver fibrosis models, after knockdown of RAB18, the colocalization of lipid droplets with α‐SMA significantly decreased." (PMID 40213908, 2025). "With the downregulation of RAB18 protein, the expression of DLD and P62 proteins also significantly decreased, indicating that RAB18 plays a key role in the regulation of liver fibrosis by modulating lipophagy and cuproptosis." (PMID 40213908, 2025). "To further explore the relationship between RAB18 and the pathological progression of liver fibrosis, we analyzed the expression of RAB18 in human liver fibrosis clinical samples." (PMID 40213908, 2025). "In the CCl4‐induced liver fibrosis model, we used GYY4137 as a positive control and set two dosing concentrations, low (15 mg kg−1) and high (30 mg kg−1), combined with AAV8‐RAB18KD treatment in mice to systematically explore the central role of RAB18 in DATs‐mediated liver fibrosis treatment." (PMID 40213908, 2025). "Targeting the regulation of RAB18 to promote lipid droplet accumulation and inhibit HSCs via the cuproptosis pathway could offer a novel therapeutic strategy for liver fibrosis." (PMID 40213908, 2025). "Therefore, abnormal regulation of RAB18 may influence the accumulation of lipid droplets, modulating the activation state of HSCs and thereby contributing to the progression of liver fibrosis." (PMID 40213908, 2025). "Next, we investigated the expression of RAB18 in two commonly used experimental liver fibrosis mouse models, including the carbon tetrachloride (CCl4)‐induced liver fibrosis model and the bile duct ligation (BDL)‐induced liver fibrosis model." (PMID 40213908, 2025). "The analysis revealed significant changes in the expression of several key genes in the model group, with notable differences in the expression of RAB18 and DLD, suggesting that these genes may play important regulatory roles in the onset and progression of liver fibrosis." (PMID 40213908, 2025).
neuroblastoma (1 paper, 2017). Neuroblastoma (NB) is the most common solid, extracranial childhood tumor. "In addition to syntaxin 18, Rab18 interacts with ZW10 kinetochore protein (ZW10) and RAD50 interactor 1 (RINT1), which, together with neuroblastoma amplified gene (NAG), are members of the NRZ complex." (PMID 28815213, 2017).
nuclear cataract (1 paper, 2014). A cataract (disease) that involves the lens nucleus. "Rab18-mutant mice develop the ocular and neurological phenotypes that are associated with the human disease, including congenital nuclear cataracts, atonic pupils and progressive hind limb weakness." (PMID 24764192, 2014). "Rab18−/− mice present at the eye-opening stage with dense nuclear cataracts and atonic pupils." (PMID 24764192, 2014).
oesophagus squamous cell carcinoma (1 paper, 2025). "Increased RAB18 expression was positively associated with poor prognosis in oesophagus squamous cell carcinoma following radiotherapy." (PMID 40381373, 2025).
paraplegia (1 paper, 2014). Complete paralysis of the lower half of the body including both legs, often caused by damage to the spinal cord. "Finally, Spartin, the Drosophila ortholog of the protein encoded by the spastic paraplegia gene SPG20 was Rab18 specific in both data sets, and we confirmed that this interaction was GTP dependent." (PMID 25453831, 2014).
parasite infection (1 paper, 2024). "Our results showed that parasite infection in macrophages were not compromised in these cells as similar number of parasites were observed in both Rab18 knock-down and miR-1914-3p overexpressed cells at 0 h." (PMID 38412149, 2024).
polymicrogyria (1 paper, 2015). A developmental brain abnormality characterized by an excessive amount of small convolutions on the surface of the brain and cognitive dysfunction. "Mutations or dysregulation of RAB18 causes Warburg Micro syndrome, which is characterized by ocular and neurodevelopmental abnormalities, including polymicrogyria, microcephaly, pachygyria, polymicrogyria, and hypoplasia of the corpus calossum." (PMID 26541977, 2015).
schizophrenia (1 paper, 2016). A major psychotic disorder characterized by abnormalities in the perception or expression of reality. "Moreover, a translational convergent functional genomics (CFG) approach has identified RAB18 as a candidate gene involved in schizophrenia." (PMID 26879639, 2016).
Spastic paraplegia (1 paper, 2014). Complete loss of the ability to move the lower limbs accompanied by spasticity of the lower limbs. "Moreover, the spatial and temporal nature of cytoskeletal accumulations closely matched the overall progression of weakness that was observed in Rab18−/− mice, which itself might correlate with the progressive spastic paraplegia that is observed in individuals with WARBM." (PMID 24764192, 2014).
Warburg syndrome (1 paper, 2014). "These include CG31935, the Drosophila ortholog of the Rab3GAP catalytic subunit whose human mutation causes the same Warburg syndrome as Rab18 mutations." (PMID 25453831, 2014).
tumor (8 papers, 2014 to 2021). "RAB1B (P<1E-12), RAB2A (P<1E-12), and RAB18 (P=2.7611E-09) were significantly up-regulated in primary tumor tissue (n=1 097) compared with that in normal tissue (n=114)." (PMID 32432324, 2020). "It is worth noting that among the genes in Set A whose expression is down-regulated abound those with tumor-inhibitory activity (e.g., Pag1, PadI4, Lats2, and Cxcl3), while among the up-regulated genes are present tumor facilitators (e.g., Rab18, Dek)." (PMID 27965576, 2016). "Down-regulation of miR-30b/c and up-regulation of Rab18 protein levels were detected in NSCLC specimens compared with adjacent non-tumor tissues." (PMID 25249344, 2014). "Down-regulation of miR-30b/c and up-regulation of Rab18 protein levels were also found in NSCLC tissues compared to adjacent non-tumor tissues." (PMID 25249344, 2014). "In this study, we first reported that Rab18 protein levels were highly expressed in NSCLC tissues compared to matched adjacent non-tumor tissues." (PMID 25249344, 2014). "It has been reported that miR-30 could target Wnt/β-catenin, EGF/Src, Myc, Rab18 and other signaling to inhibit tumor growth." (PMID 31382411, 2019). "Compared with normal breast tissue, miR-200b expression was down-regulated in tumor tissue, while the contrary situations were found for RAB21, RAB23, RAB18 and RAB3B IHC staining." (PMID 24447584, 2014). "In our study, we showed that Rab18 were identified as direct functional targets of miR-30b/c in NSCLC cells and miR-30b/c was down-regulated in NSCLC tissues compared to adjacent non-tumor tissues." (PMID 25249344, 2014). "In summary, miR-200b low ISH staining was seen in 90% (9/10) tumor samples, while positive rates for RAB21, RAB23, RAB18 and RAB3B IHC staining were 80%, 80%, 90%, 100% respectively." (PMID 24447584, 2014). "Although some candidate markers, such as Rab1, Rab18, and Ezrin which are elevated in HCC, were reported to promote HCC progression, the oncogenic or tumor-suppressive roles of other candidate proteins we found in HCC tissues remain unclear." (PMID 33888099, 2021).
cancer (7 papers, 2014 to 2025). A tumor composed of atypical neoplastic, often pleomorphic cells that invade other tissues. "Emerging evidences have revealed the association between dysfunction of the Rab18 and multiple human diseases including cancer." (PMID 25249344, 2014). "The roles of Rab18 in proliferation and apoptosis have been widely investigated in some cancers." (PMID 33904378, 2021). "Interestingly, these three genes (RAB1B, RAB2A, and RAB18) have been studied in several malignant tumors." (PMID 32432324, 2020). "Moreover, STAT3/Rabs-mediated exosome release was correlated with a more aggressive and chemoresistant cancer phenotype under hypoxic conditions and a recent study demonstrated a role for Rab18 in resistance to cisplatin-induced apoptosis." (PMID 32823947, 2020). "However, the expression of Rab18 is less well known in human cancers especially in NSCLC." (PMID 25249344, 2014).
infection (7 papers, 2013 to 2024). The state of being infected such as from the introduction of a foreign agent such as serum, vaccine, antigenic substance or organism. "After infection, RAB18 expression was increased in both the wild-type and the pGC1::SNC1-1 cells but the expression in pGC1::SNC1-1 was still much lower than that in the wild type." (PMID 31652291, 2019). "The results revealed the importance of Ras-related protein Rab18 and syntaxin 18 for BKPyV infection." (PMID 28815213, 2017). "Knockdown of Rab18 and syntaxin 18 reduced TAg expression, indicating that both proteins are required for efficient infection." (PMID 28815213, 2017). "About 90% Ld-PVs were found to be positive for Rab18 after 24 h infection in macrophages." (PMID 38412149, 2024). "Interestingly, we found that L. donovani induce more than 2-fold expression of Rab18 in macrophages after 24 h of infection compared to uninfected control." (PMID 38412149, 2024). "After CSFV (MOI = 5) infection, we observed that Rab18 silencing impaired viral RNA replication." (PMID 32419589, 2020). "Several other Rabs displaying close phylogenetic relationship to Rab1, including Rab8, Rab18, Rab35, Rab33, Rab30, Rab19, and Rab37, could also be modified by SseK3 upon infection." (PMID 32504010, 2020). "The Rab18/NRZ/syntaxin 18 complex is required for BKPyV infection." (PMID 28815213, 2017). "To understand the mechanism of upregulation of Rab18 and TRAPPC9 expression in L. donovani infected macrophages, we focused on the modulation of miRNA expression as several intracellular pathogens alter the expression of host miRNAs to establish infection." (PMID 38412149, 2024). "In the meantime, the expression of RAB18 in whole leaves was only slightly higher but not significant in pGC1::SNC1-1 than in Col-0 without infection." (PMID 31652291, 2019). "Quantitative RT-PCR analysis also revealed that the expression of RAB18 in enriched guard cells of the pGC1::SNC1-1 line was lower than that of wild-type Col-0 without pathogen infection." (PMID 31652291, 2019).
neurodevelopmental disorder (2 papers, 2022 to 2023). A behavioral and cognitive disorder with onset during the developmental period that involves impaired or aberrant development of intellectual, motor, or social functions. "Rab18 has specifically been implicated in secretory pathway regulation, and RAB18 variants are associated with a neurodevelopmental disorder phenotypically overlapping TRAPPC10-related disorder." (PMID 35298461, 2022).
RAB18 also shares sentences with these, for which no sentence is quoted: Martsolf syndrome (4 papers); allergic reactions (1); cardiac failure (1); Cerebral atrophy (1); COVID-19 (1); genetic disorders (1); head and neck squamous cell carcinoma (1); Hyperglycemia (1); Hyperinsulinemia (1); hypogonadism (1); Intellectual disability (1); leishmaniasis (1); microphthalmia (1); Neurodevelopmental delay (1); pancreatic cancer (1); type II diabetes (1); Warburg micro syndrome 1 (1).